RNU6-236P (RNA, U6 small nuclear 236, pseudogene)
Gene: Small nuclear RNA gene on chromosome 5 (139,717,985 to 139,718,090, reverse strand). Ensembl gene ENSG00000200756.
Homologues: Orthologues: chimpanzee U6 (96% identical). Paralogues in human: RNU6-1075P (90% identical), RNU6-1060P (88% identical), RNU6-29P (88% identical), RNU6-348P (88% identical), RNU6-41P (88% identical), RNU6-74P (88% identical), RNU6-842P (88% identical), RNU6-1117P (87% identical), RNU6-116P (87% identical), RNU6-147P (87% identical), RNU6-266P (87% identical), RNU6-338P (87% identical), and 1284 more.